DEXI (Dexi homolog)
Synonyms: MYLE
Tractability: No criterion of Open Targets' tractability assessment is met for any kind of drug.
Gene: Protein-coding gene on chromosome 16 (10,928,891 to 10,942,468, reverse strand). Ensembl gene ENSG00000182108.
Subcellular location (Human Protein Atlas): Nuclear speckles; Cytosol
Gene Ontology:
Molecular function: protein binding
Genetic constraint (gnomAD): Loss-of-function variants: 2 observed, 2.46 expected, observed/expected ratio (o/e) 0.81, 90% interval 0.31 to 1.82. That is too few expected variants to judge how well the gene tolerates losing a copy. Missense variants: 108 observed, 125.63 expected, observed/expected ratio (o/e) 0.86, 90% interval 0.74 to 1.01. Synonymous variants: 71 observed, 64.45 expected, observed/expected ratio (o/e) 1.1, 90% interval 0.91 to 1.34.
Homologues: Orthologues: chimpanzee DEXI (100% identical), macaque DEXI (99% identical), dog DEXI (97% identical), pig DEXI (97% identical), mouse Dexi (95% identical), rat Dexi (95% identical), guinea pig DEXI (94% identical), tropical clawed frog DEXI (68% identical), zebrafish dexi (67% identical).
Diseases named in the same sentence as DEXI in open-access papers:
DEXI is named in the same sentence as 9 diseases in open-access papers, as found by Europe PMC text mining. Sharing a sentence is not in itself a finding about the gene and the disease.
DEXI shares sentences with these, for which no sentence is quoted: autoimmune disease (2 papers); multiple sclerosis (2); systemic lupus erythematosus (2); alopecia areata (1); asthma (1); celiac disease (1); lymphoma (1); psoriasis (1); type-I diabetes (1).